CDC42 (cell division cycle 42)
Diseases named in the same sentence as CDC42 in open-access papers (continued):
Sharing a sentence is not in itself a finding about the gene and the disease.
cancer (continued). "The exact mechanism for this cancer development is still not well understood, but it might be due to the ability of RhoH to regulate the activities of other cancer-related small Rho GTPases, including RhoA, Cdc42, Rac1 and RhoF." (PMID 33923951, 2021). "Most of the biological consequences of the Cdc42 mutations identified in cancer have not been determined but it is useful to consider what the manifestation of these mutations could be in terms of function." (PMID 34196668, 2021). "Given that the cancer associated mutations in Cdc42 are not likely to predominantly affect deactivation mechanisms, as is found for K-Ras, selectivity for Cdc42 in both nucleotide forms may have therapeutic relevance." (PMID 34100887, 2021). "CDC42 has previously been proven to regulate mechanotransduction responses, such as endothelial migration, osteoblast β-catenin signaling, integrin signaling, morphology and differentiation of mesenchymal stem cells, and stiffness-induced dormancy of cancer cells." (PMID 32532057, 2020). "In addition to combined therapy with existing cancer therapeutics, cocktails of Rac/Cdc42 GEF targeting compounds may also be developed for maximum therapeutic efficacy." (PMID 32322580, 2020). "We now provide pharmacological evidence that the CTD Ser2 and Ser5 phosphorylation status could be altered by inhibitors of Ras, as well as Rho, Rac and Cdc42, in human cancer cell lines, supporting a common theme for the Ras superfamily of GTPases-mediated modulation of the Pol II CTD code." (PMID 32143485, 2020). "Overall, this review provides ample evidence for the utility of Rac/Cdc42 inhibitors both individually, and in combination with current targeted and cytotoxic therapeutics to overcome therapy resistance and augment established cancer therapies to specifically block metastasis." (PMID 32322580, 2020). "In addition to modulation of the transforming activities of oncogene, Cdc42 may also function as tumor suppressor in several human cancers." (PMID 32392742, 2020). "Therefore, Rac and Cdc42 activation, even in the absence of oncogenic mutations or dysregulated expression, can play a critical role in cancer progression to metastasis." (PMID 32322580, 2020). "Moreover, inhibition of CDC42 was regarded as a therapeutic target in cancers." (PMID 31889909, 2019). "CDC42SE1 is a small effector of CDC42 and their function in cancer remains unknown." (PMID 30717410, 2019). "Previous studies showed that Cdc42 and Borgs regulate protrusion formation induced by actin-depolymerizing toxins and thus we were interested to see whether the same mechanism is employed in microtentacle formation in cancer cells." (PMID 29100341, 2017). "Consequently, we hypothesize that Rac1/Cdc42 inhibition by AZA1 treatment increases cancer cell apoptosis involving the PAK-AKT-BAD signaling pathways." (PMID 24040362, 2013). "Since IQGAP1 has been shown to associate with various small GTPases including cdc42 and Rac1, we examined whether or not RalA, previously shown to signal downstream of β-arrestin in cancer cells, can associate with IQGAP1." (PMID 23405264, 2013). "To determine whether Cdc42 could interact with more physiologically relevant versions of APC we carried out FRET experiments with full-length APC and a truncation mutant linked with cancer, APC1–1638." (PMID 21311754, 2011). "Furthermore, our study elucidates that the expression of several highly significant cancer related genes require the activities of Rac1 and/or Cdc42 which may also play a critical role in cellular transformation." (PMID 20067638, 2010). "Of note, similar to GNB1 both CDC42 and CHD5 were found to be highly methylated (methylated read count >700) in the BOCA-FR cancer cohort." (PMID 41345172, 2025). "Among the top anticorrelated genes were SLC38A2 and CDC42, the latter of which has previously been shown to be downregulated by MIR137 in cancer cells." (PMID 40964041, 2025).
cancer (continued). "Although we focused on RBM15 and serine metabolism in this study, network analysis revealed that the relationship between RBM15 and other genes with oncogenic potential (CDC42, CDC14B, STK40, BRD3, CPNE1, and MCM3) is also crucial for cancer cell survival." (PMID 38825643, 2024). "It was reported that GRAF1 regulated the expression of CDC42, which was able to activate the PAK1/MAPK pathway and led to the migration and invasion of cancer cells." (PMID 36849460, 2023). "Among these genes, CDC42 and ANXA10 are upregulated in various human cancer cell lines and their expression correlates with tumor stage, lymph node metastasis, and patient survival." (PMID 37833712, 2023). "Apart from cancer cells, we were also able to confirm that ERK3 sustains the activity of RAC1 and CDC42 in primary human umbilical vein endothelial cells, HUVECs." (PMID 37057894, 2023). "NETs‐DNA enhanced endogenous binding of ITGB4 to integrin‐linked kinase (ILK), a putative mediator of NETs‐driven cancer metastasis, leading to recruitment of β‐parvin, but not α‐parvin or PINCH, to mobilize the small GTPases RAC1 and CDC42." (PMID 37828611, 2023). "CDC42 was proved to regulate EMT and cancer metastasis, and activate PAK1 (a serine/threonine protein kinase) which was involved in various tumor signaling pathways including MAPK." (PMID 36849460, 2023). "Our results support LINC00339 and CDC42/CDC42-AS1 as the most likely candidate genes in this locus, which is in line with evidence from other cancers." (PMID 36929174, 2023). "The Rac and Cdc42 inhibitors, EHop-016 and MBQ-167, are potent inhibitors of cancer cell migration and metastasis, as our group has demonstrated in different cancer cell types." (PMID 37397366, 2023). "IQGAP1 is a crucial regulator of cancer development by scaffolding and facilitating different oncogenic pathways, especially RAC1/CDC42, thus affecting proliferation, adhesion, migration, invasion, and metastasis." (PMID 37787041, 2023). "In support of these findings, HCC patients with higher levels of RAC1, CDC42, and PAK1 show worse overall survival, which can be attributed to enhanced macropinocytosis and resistance to cancer therapy." (PMID 35287706, 2022). "In the PPI network, the core targets, including AKT1, CREB1, CDC42, SIRT1, PIK3CA, and MMP9, are key cancer‐related genes, which further indicate the important role of miR‐204‐5p in human cancers." (PMID 35908280, 2022). "RAC1/CDC42 also promotes HCC EMT and metastasis via PAK1, which induces cancer metastasis via the phosphorylation of paxillin and activation of JNK." (PMID 36348464, 2022). "In the new landscape of cancer genomics, activating point mutations in members of the RHO GTPases have been identified, in particular in RAC1, RHOA, and CDC42, which has suggested that RHO GTPases can indeed serve as oncogenes in certain cancer types." (PMID 35454871, 2022). "Cdc42 can activate ACK1 by directly and specifically binding to it 48, which enables cells to bypass the blockade to major survival pathways to promote cancer progression and resistance to standard cancer treatments." (PMID 35154449, 2022). "Activated Rac and Cdc42 bind to the PAK effector protein and transmit signaling and promote motility, invasion, and metastasis of cancer cells." (PMID 35110666, 2022). "The essential downstream regulator of RAC1 and CDC42 is PAK, which plays vital roles in cancer initiation, growth, angiogenesis, immunity, metabolism, metastasis, and drug resistance." (PMID 35433481, 2022). "Meanwhile, in cancer cells, GLK directly phosphorylates and activates IQGAP1, resulting in the induction of Cdc42-mediated cell migration and cancer metastasis." (PMID 36605209, 2022).
cancer (continued). "The NSC23766 derivative AZA197 at 1–10 μmol/L inhibited the Cdc42-GEF Dbs activity and thus, colon cancer cell proliferation, and cancer progression in mice." (PMID 36861094, 2022). "OGR1-induced up-regulation of CK2αP through activation of small GTPase, Rac1/cdc42, and ERK/JNK/p38 pathways are responsible for inhibition of cancer cell migration." (PMID 35123428, 2022). "In sum, these results explain the phenotypic change in cancer cells and indicate an inhibitory role of NDRG1 in actin reorganization and cell invasiveness via a CDC42/PAK1/Cofilin dependent pathway." (PMID 33994856, 2021). "PAK5, a CDC42/RAC1-dependent activated kinase is upregulated in CRC versus adjacent tissue, and this is correlated with cancer progression." (PMID 33406731, 2021). "The importance of Cdc42-MRCK and RhoA-ROCK1/2 in both polarity and cell motility place them as important factors in both normal cellular processes and cancer." (PMID 34008470, 2021). "While none of the inhibitors targeting these GTPases have been approved for cancer therapy to date, RAC1/Cdc42 inhibition as a strategy to overcome therapy resistance has been validated previously." (PMID 33603169, 2021). "For instance, POTEE is upregulated in CRC, and it promotes cancer cell proliferation and tumor growth and metastasis in vivo by activating RAC1 and CDC42." (PMID 33406731, 2021). "ITSN1 has been identified as a Cdc42 specific GEF in in vitro studies and is one of several RhoGEFs showing a high frequency of alterations in some cancer types." (PMID 34100887, 2021). "In conclusion, we show that cancer cell surface CD99 modulates tumour cell TEM and metastatic progression, and we identify CD99 as a negative regulator of CDC42 activity." (PMID 34374417, 2021). "Our data suggest that, by stabilizing the complex of RhoGDIα and CDC42, NDRG1 plays a crucial role in keeping CDC42 in the inactive form and thereby prevents filopodia formation and cancer cell invasion." (PMID 33994856, 2021). "Predicted genes targeted by dysregulated oncomiRs or tumor suppressor miRNAs were mainly involved in cell cycle regulators such as CAPRIN1, CDC42, PTEN, IGF1R, BRCA1 and CD28, thereby controlling cancer dormancy." (PMID 33374139, 2020). "According to the database annotation, universal EV proteins (CDC42, GNAI2, ITGB3, TLN1, and TUBA4A) are involved in platelet activation that help cancer cells escape immune surveillance and provide a prometastatic microenvironment." (PMID 32916986, 2020). "Due to the specificity of their interaction with different oncogenic GEFs, drugs that block the Rac/Cdc42-GEF interaction need to be prudently targeted to different tissues and types of cancer according to their expression and activation of specific GEFs." (PMID 32322580, 2020). "However, phenanthriplatin may also act to prevent cancer cell cytoskeletal stability by downregulating DIAPH2, while cisplatin regulation of cancer cell microtubule stability may act instead through microRNA and CDC42 signaling to modulate A549 cancer cell proliferation." (PMID 33302475, 2020). "Here, we present genetic and pharmacological evidence showing that Cdc42 and Rac1 GTPase signaling modulates a similar CTD Ser2 and Ser5 phosphorylation code in cultured human cancer cells." (PMID 32143485, 2020). "CDC42 is a member of the Rho family of small GTPases and is activated by CD47 to serve as a crucial regulator of cancer metastasis." (PMID 32314789, 2020). "A recent study on human carcinoma cell showed that EIPA can block the activation of the Rac1 and Cdc42 signaling pathways by lowering submembranous pH, therefore, macropinocytosis pathway was inhibited." (PMID 31449523, 2019). "Clathrin, caveolin, Rabs (Rab4, Rab5A, Rab1A, Rab2A) as well as their effectors (Rab25, Vav1, Rab coupling protein,cdc42, VSP39), can contribute to the processes of cancer cell survival and metastasis, and cancer stem cell emergence." (PMID 29409507, 2018).
cancer (continued). "CDC42, RAC1, and RHOA are well characterized for actin reorganization, cancer invasion, and metastasis in various cancers but are still incompletely characterized in ESCC." (PMID 30327774, 2018). "There is consensus that the Rho A family and CDC42-Rac signaling, play independent roles in the various stages of actin reorganization, while COX2 and MMPs are involved in tumor invasion by many cancer types." (PMID 28800782, 2017). "The “mesenchymal” movement (elongated movement of cancer cells) requires activation of RAC1, whereas rounded/amoeboid movement engages specific Cdc42 signaling pathways." (PMID 27902969, 2017). "Altogether, our study supports an oncogenic role of CDC42 in CRC by the transcriptional deregulation of key genes and pathways involved in several cancer-related processes." (PMID 28460460, 2017). "These include cancer hallmarks of various types: oncogenes (BCL2, BRAF), caspases (CASP6/7), transcription factors (E2F3), cell cycle genes (CDC42, CDK2, CDKN2A), cancer related kinases (JAK2/3, MAPK4/6/14) and DNA repair genes (BRCA1, PARP1 and RAD50)." (PMID 28059167, 2017). "As indicated by our results, the mRNA expression levels of SRC, CDC42, WASL, and RHO were all changed during cancer cell migration." (PMID 28640862, 2017). "This is consistent with observations in cancer cell lines, where external cues such as the EGF growth factor and collagen I fibers are thought to stimulate activation of Cdc42 and invadopodia formation." (PMID 26765257, 2016). "For example, Rho GDP dissociation inhibitors (RhoGDIs) have been shown to play a role in cell migration and cancer progression by preventing the exchange of a GDP nucleotide for GTP, thus inhibiting Cdc42 and other Rho family members, such as Rho and Rac." (PMID 27341132, 2016). "By targeting DNMT1, RhoA/Cdc42, and E2F6, miR-185 has been shown to induce cell cycle arrest and apoptosis, in addition to inhibiting proliferation and invasion in cancer cell lines and xenograft mouse models of various cancers." (PMID 26930719, 2016). "Published results suggest that blocking IQGAP1-CDC42 and IQGAP1-RAC1 complex formation will decrease the amount of active forms of CDC42 and RAC1 in carcinoma cells and thus reduce tumorigenesis." (PMID 27815503, 2016). "HeLa cells were used as an independent cancer-relevant, human cell line to test the full chemical series (R-naproxen, S-naproxen, and 6-MNA) for effect on Rac1 and Cdc42 activation using the G-trap assay." (PMID 26558612, 2015). "We provide evidence that CA’s anti-cancer effects stem from its anti-migratory effect, by blocking the VEGFR2 ATP binding pocket and down-regulating the downstream Src/FAK/cdc42 signaling axis." (PMID 25978354, 2015). "Rac1/Cdc42 overexpression also has been correlated with poor clinical outcome in NSCLC and other cancers." (PMID 26462147, 2015). "MiRNAs can notably regulate whole biological pathways; for example, miR-181 controls mouse hematopoiesis, miR-608 targets two inflammation-related transcripts, CDC42 and IL6 and miR-221 controls multiple cancer pathways." (PMID 24574962, 2014). "Our findings are in keeping with previous reports showing the importance of RhoA, Rac1 and Cdc42 in cancer progression, and also the crosstalk between these GTPases and other signaling pathways like Src-FAK in the migratory phenotype of cancer cells." (PMID 23799130, 2013). "For example, deletion of liver cancer 1 (DLC-1), a RhoA and Cdc42-specific GAP, inhibits the growth of various types of cancer, including lung, breast, prostate, kidney, colon, uterus, ovary and stomach through altering the actin cytoskeleton." (PMID 23538840, 2013). "Super-EBS treatment inhibited Rac-1, Cdc42 and p-PAK1 expression levels in both cancer cell lines." (PMID 39781466, 2025). "This further supports Cdc42 as a potential therapeutic target for cancer treatment, especially in TNBC, which does not respond to most therapies." (PMID 38612766, 2024).
cancer (continued). "Additionally, the combination of DHA and RES can regulate the JNK/NF-κB and N-WASP signaling pathways through Cdc42, inhibiting F-actin formation and impeding the migration of HepG2 and MDA-MB-231 cancer cells." (PMID 38835077, 2024). "Because CCDC85A upregulated TGFβ in cancer cells under the hypoxic conditions, it may promote EMT and activate Rac1/CDC42." (PMID 37534255, 2023). "Moreover, miR-29s induced apoptosis in cancer cells by negatively regulating anti-apoptotic proteins such as MCL-1, VDAC1/2, and CDC42/p85 complex." (PMID 36140219, 2022). "Here, we systematically reviewed the structure, functions, and small molecule inhibitors of Cdc42 in malignant tumor and non-tumor diseases, providing specific targets for the treatment of Cdc42-related diseases." (PMID 35154449, 2022). "The invasion of cancer cells to the perivascular environment relies on their motility, in which motility-involving molecules such as ARP2/3, L1CAM, serpins, CD44, CDC42, CXCR4, epidermal growth factor receptor (EGFR), as well as Wnt7 signaling, are critical players." (PMID 36119528, 2022). "Cancer cell migration includes several mechanistic pathways such as FAK, AKT, and Cdc42." (PMID 36500213, 2022). "The interaction between Cdc42 and IQGAP1 enhances migration and invasion of cancer cells." (PMID 36253497, 2022). "However, Cdc42 depletion was able to reverse the effect of StarD13 depletion in SKOV-3 and Caov-3 cancer cells and reduce the number of invaded cells by around 50% as compared to the StarD13 depleted cells." (PMID 34958986, 2022). "However, in tumor cells, the high expression of activated Cdc42, abnormal ubiquitin ligase, and EGFR degradation inhibition result in malignant tumor progression." (PMID 35154449, 2022). "Another interesting approach could be to suppress CD44 and CDC42, which might impair VCO by impeding the cancer cell-pericyte fusion." (PMID 36119528, 2022). "Because the Rac/Cdc42 inhibitor MBQ-167 induces cell-cycle arrest and subsequent apoptosis, we tested the effect of the MBQ-167 derivatives on apoptosis via analysis of caspase-3/7 activity in cancer cell lines." (PMID 36861094, 2022). "Notably, the CDC42/PAK1 complex offers a wealth of structural,mutagenesis, and binding affinity data because of its central rolein cellular signaling and cancer progression." (PMID 35679463, 2022). "Furthermore, in several types of cancer cells, DOCK7 (an XYZ) binds to the cytoplasmic domain of RAGE and leads to Cdc42 activation." (PMID 34199060, 2021). "More significantly, collagen/fibronectin could facilitate the activation of PI3K/AKT/SOX2 and CDC42/YAP-1/NUPR1/Nestin signaling pathways via integrin αvβ3, eliciting sustained tumor growth and cancer relapse." (PMID 33408794, 2021). "In cancer therapy a drug candidate named "Rhosin" has been designed, which effectively inhibits the Rho-subfamily of Rho GTPases, without affecting Rac1 or Cdc42." (PMID 33906663, 2021). "The migratory machinery of cancer cells is depended on interactions between specific cell cytoskeletal proteins coordinated by small GTPases, such as the Rho family of proteins (RHOA, CDC42 and RAC-1." (PMID 34321041, 2021). "CDC42 activation is also required for EGF-induced cell migration and protrusion in carcinoma cells." (PMID 33672558, 2021). "Silencing of CDC42 with two independent siRNAs strongly impaired the formation of invadopodia and collagen degradation by MDA-MB-231 cells, confirming that CDC42 is a master regulator of invadopodia formation and activity in cancer cells." (PMID 32673397, 2020). "If CD47 controls Cdc42 expression in NSCLC cells, and Cdc42 in turn mediates the invasive phenotype of these cancer cells, then blocking CD47 or inhibiting Cdc42 expression may become a new method of inhibiting the metastasis of NSCLC cells." (PMID 32082311, 2020). "CDC42 and EGFR have been used as potential targets for angiogenesis and cancer therapies." (PMID 32545766, 2020).